DLX5 (distal-less homeobox 5)
Diseases named in the same sentence as DLX5 in open-access papers (continued):
Sharing a sentence is not in itself a finding about the gene and the disease.
lymphoma (continued). "Moreover, Akt signaling and c-Myc levels are consistently elevated in Dlx5-induced lymphomas, and pharmacological inhibition of Akt and c-Myc triggers these lymphoma cells to undergo apoptosis." (PMID 34203994, 2021). "Previous studies have reported that DLX5 is upregulated in human lymphomas and non-small cell lung cancer, where it could bind to the MYC promoter to activate its transcription." (PMID 34336814, 2021). "Additionally, treatment of lymphoma cells from Lck-Dlx5;Lck-MyrAkt2 mice with β-catenin/Tcf inhibitors demonstrated that β-catenin signaling plays a critical role in promoting cell survival." (PMID 32985581, 2020). "However, upregulation of genes involved in the Wnt pathway and cholesterol synthesis were unique to the lymphomas from the Lck-Dlx5;Lck-MyrAkt2 mice." (PMID 32985581, 2020). "This marked acceleration of tumor onset and progression appears to result from the unique activation of β-catenin signaling in lymphoma cells from Lck-Dlx5;Lck-MyrAkt2 mice, as activation of Akt, Notch, and Myc were common to the lymphomas from mice with all three genotypes." (PMID 32985581, 2020). "Moreover, flow cytometric analysis revealed a marked increase in apoptotic sub-G1 cells, suggesting that Wnt signaling plays an essential role in the survival of Lck-Dlx5;Lck-MyrAkt2 lymphoma cells." (PMID 32985581, 2020). "Lymphoma cells from Lck-Dlx5;Lck-MyrAkt2 mice were treated with PFK118-310 at 1 μM for 20 h and then subjected to whole transcriptome analysis, which revealed altered expression of genes encoding Srebf2-cholesterol synthesis pathway members and cell cycle regulators." (PMID 32985581, 2020). "Notably, expression of Ptk2/Fak was upregulated in both Lck-Dlx5- and Lck-MyrAkt2-derived lymphomas." (PMID 28122332, 2017). "Further upregulation of Notch1/3 protein levels was observed in Lck-Dlx5 lymphoma cells." (PMID 28122332, 2017). "Integrated ChIP-seq and mRNA microarray analyses identified Notch1/3 and Irs2 as direct transcriptional targets of Dlx5, a gene signature unique to lymphomas from Lck-Dlx5 mice as compared to T-cell lymphomas from Lck-MyrAkt2 mice, which were previously reported by our group." (PMID 28122332, 2017). "We used Affymetrix microarrays to assess mRNA expression patterns in Lck-Dlx5 lymphomas." (PMID 28122332, 2017). "Immunoblotting uncovered upregulation of Notch1/Notch3 in tumors from Lck-Dlx5 and Lck-Dlx5;Lck-MyrAkt2 mice, upregulation of Myc in tumors from Lck-Dlx5, Lck-MyrAkt2, and Lck-Dlx5;Lck-MyrAkt2 mice, and upregulation of β-catenin uniquely in lymphomas from Lck-Dlx5;Lck-MyrAkt2 mice." (PMID 32985581, 2020). "NIC1 specific antibody (Val1744) also revealed high levels of NIC1 in lymphoma cells from Lck-Dlx5 mice, but no expression in tumors cells from Lck-MyrAkt2 mice." (PMID 28122332, 2017). "The reason why mRNA levels of Notch1 and Notch3 were 2–4 fold greater in lymphoma cells than in normal T cells from Lck-Dlx5 mice was not due to gene amplification, as array-CGH analysis revealed no change of Notch1/3 gene copy number." (PMID 28122332, 2017). "One possible reason for this is that a Notch1/3 enhancer-specific coactivator generally may be lacking in Lck-MyrAkt2 lymphoma cell lines expressing Dlx5." (PMID 28122332, 2017). "Interestingly, although expression of Pten protein was absent in Lck-Dlx5 lymphoma cells, these cells were still sensitive to Notch inhibitors." (PMID 28122332, 2017).
osteoarthritis (6 papers, 2019 to 2025). A noninflammatory degenerative joint disease occurring chiefly in older persons, characterized by degeneration of the articular cartilage, hypertrophy of bone at the margins and changes in the synovial membrane. "DLX5 has been reported to regulate chondrocyte hypertrophy, which is associated with osteoarthritis, a chronic inflammatory condition." (PMID 40705171, 2025). "The pharmacological inhibition of DLX5 by administration of DLX5-blocking antibodies reduced the cartilage calcification associated with osteoarthritis in rabbits along with the gene expression of alkaline phosphatase." (PMID 36291143, 2022). "Similarly, DLX5, a nuclear transcription factor, plays an important role in anti-inflammation by avoiding chondrocyte hypertrophy, which is associated with osteoarthritis." (PMID 40705171, 2025). "Our findings also indicate that Dlx5 may become a clinical diagnostic marker for osteoarthritis." (PMID 35280506, 2022). "Here, we found that Dlx5 treatment indeed retarded osteoarthritis progression by inhibiting chondrocyte hypertrophy and chondrocyte apoptosis." (PMID 35280506, 2022). "Chondrocyte hypertrophy, chondrocyte apoptosis, and extracellular matrix damage, which were increased in cartilages of osteoarthritis, were all reduced after anti-Dlx5 treatment." (PMID 35280506, 2022). "Next, we investigated the mechanism by which anti-Dlx5 treatment ameliorated papain-induced osteoarthritis." (PMID 35280506, 2022). "In conclusion, anti-Dlx5 retarded the progression of osteoarthritis by downregulating chondrocyte hypertrophy and chondrocyte apoptosis-related genes." (PMID 35280506, 2022). "The results showed that administration of anti-Dlx5 improved pathological changes of osteoarthritis cartilages, characterized by decreased chondrocyte proliferation, chondrocyte hypertrophy, and matrix damage." (PMID 35280506, 2022). "Here, we found that anti-Dlx5 treatment retarded the progression of osteoarthritis by inhibiting chondrocyte hypertrophy, chondrocyte apoptosis, and matrix damage, suggesting that Dlx5 is a promising target for osteoarthritis treatment." (PMID 35280506, 2022). "In summary, anti-Dlx5 retards the progression of osteoarthritis by inhibiting chondrocyte hypertrophy and chondrocyte apoptosis." (PMID 35280506, 2022). "Our study aimed to investigate the role of Dlx5 in papain-induced osteoarthritis." (PMID 35280506, 2022). "It has been reported that Dlx5 is upregulated in osteoarthritis cartilage." (PMID 35280506, 2022). "Given that chondrocyte hypertrophy can lead to the progression of osteoarthritis, we hypothesized that Dlx5 might play an important role in osteoarthritis progression." (PMID 35280506, 2022). "Collectively, administration of anti-Dlx5 could inhibit the expression of genes related to chondrocyte hypertrophy and apoptosis and thereby retard the progression of osteoarthritis." (PMID 35280506, 2022). "In this study, we found that anti-Dlx5 treatment improved papain-induced osteoarthritis." (PMID 35280506, 2022). "Our findings suggests that Dlx5 is a promising target for osteoarthritis treatment." (PMID 35280506, 2022). "Moreover, it has been reported that Dlx5 is upregulated in osteoarthritis cartilage." (PMID 35280506, 2022). "Hence, Dlx5 may be used as a potential target for the treatment of osteoarthritis." (PMID 35280506, 2022). "Our data suggest that PS77 may be a potential therapeutic agent for osteoarthritis by downregulating BMP5 and DLX5, thereby suppressing the expression of pro-inflammatory cytokines." (PMID 40705171, 2025). "By downregulating DLX5, PS77 may help to mitigate inflammation in osteoarthritis." (PMID 40705171, 2025). "However, whether Dlx5 plays a role in osteoarthritis progression has not been investigated." (PMID 35280506, 2022).
preeclampsia (6 papers, 2019 to 2026). Preeclampsia is a hypertensive disorder of pregnancy that is characterized by new-onset hypertension with proteinuria presenting after 20 weeks of gestation, and depending on mild or severe forms may initially present with severe headache, visual disturbances, and hyperreflexia. "Additionally, DLX5 is upregulated in preeclamptic placentas, presumably due to altered methylation at the DLX5 locus in preeclampsia that results in loss of imprinting." (PMID 30935390, 2019). "Given the association between DLX5/GATA3 dysregulation and elevated PSG9 levels, along with PSG9's expression in the first trimester, PSG9 shows potential as a predictive biomarker for preeclampsia." (PMID 41796334, 2026). "Researchers showed that distal-less homeobox 5—DLX5 (role in tissue damage repair) and GATA binding protein 3 (GATA3) (associated with cell biology), both paternally imprinted genes, were dysregulated in placenta tissues from women with preeclampsia and endometriosis." (PMID 34833476, 2021).
schizophrenia (6 papers, 2019 to 2024). A major psychotic disorder characterized by abnormalities in the perception or expression of reality. "A large-scale transcriptomic analysis of post-mortem brains has shown that the DLX5/6 locus participates in genetic modules altered in GABAergic neuronal function in autism spectrum disorders (ASDs) and schizophrenia." (PMID 39120293, 2024). "Alterations in regulons involving DLX5/6 or DLX6-AS1 have been implicated in psychiatric disorders such as autism and schizophrenia, as well as Alzheimer’s disease and major depressive disorders." (PMID 39120293, 2024). "We previously reported some characteristic features of schizophrenia (SZ) in GABAergic neuron-specific Pgc-1alpha knockout (KO) mice (Dlx5/6-Cre: Pgc−1alphaf/f)." (PMID 37822967, 2023). "Recently, a large-scale transcriptomic study on post-mortem brains has suggested that the DLX5/6 locus participates in genetic modules altered in ASDs and schizophrenia." (PMID 35681437, 2022). "Adolescent mice, heterozygous for a generalized deletion of Dlx5 and Dlx6 (Dlx5/6+/-), present traits reminiscent of human schizophrenia, but also gonadal, bone and craniofacial anomalies not directly associated to GABAergic interneurons." (PMID 31514171, 2019). "Although these findings suggest that a reduction in Dlx5/6 expression could represent a good functional model of schizophrenia, the density of PV-interneurons in the prefrontal cortex of Dlx5/6+/− mice was not measured." (PMID 35681437, 2022). "Taken together, we posit that the decrease in Dlx1, Dlx5, and Lhx6 expression that we observed in our schizophrenia models may lead to the cell-specific deficits in interneuron development that are thought to play a key role in the pathophysiology of schizophrenia." (PMID 32497066, 2020).
autism (5 papers, 2005 to 2024). Persistent deficits in social interaction and communication and interaction as well as a markedly restricted repertoire of activity and interest as well as repetitive patterns of behavior. "The human DLX genes are organized as bigene clusters on chromosomes 2q31.1 (DLX1/2) and 7q21.3 (DLX5/6) and their expression is controlled by intra- and extragenic enhancers These genes are close to loci that have been linked with autism (2q32, and 7q22-31)." (PMID 16266434, 2005). "Thus it is interesting that both the DLX1/2 and DLX5/6 loci have been implicated in autism via independent studies, including a common polymorphism in the DLX5/6 enhancer itself." (PMID 21765815, 2011). "The fact that 4.4% of autistic probands had non-synonymous DLX2 and DLX5 variants (5% when including the DLX5/6 intergenic enhancer variant) could reflect the multifactorial etiology of autism." (PMID 16266434, 2005). "Linkage studies in autism have identified susceptibility loci on chromosomes 2q and 7q, regions containing the DLX1/2 and DLX5/6 bigene clusters." (PMID 16266434, 2005). "Given the location of DLX1/2 and Dlx5/6 in relation to autism linkage intervals, other groups have examined whether DNA variants in these genes are significantly associated with autism." (PMID 16266434, 2005). "Chromosome 7q, also an important region in linkage studies of autism, contains DLX5 and DLX6." (PMID 16266434, 2005). "While the identification of variants that generate non-conserved amino acid changes in DLX2 and DLX5 in autistic people suggests that the DLX genes could contribute to autism susceptibility, there are limitations to our study." (PMID 16266434, 2005). "Finally, perhaps the variants in DLX2, DLX5 and ARX, all of which alter the development of forebrain GABAergic neurons, are providing a clue that an increase in the ratio of excitation/inhibition underlies some forms of autism." (PMID 16266434, 2005).
T-cell lymphomas (5 papers, 2017 to 2025). "This synergism is likely due to the fact that β-catenin is strongly expressed and resides in nucleus of the T-cell lymphomas from the Lck-MyrAkt2;Dlx5 double transgenic mice." (PMID 34203994, 2021). "In several mouse models of T-cell lymphoma, Dlx5 has been shown to act as an oncogene by cooperating with activated Akt, Notch1/3, and/or Wnt to drive tumor formation." (PMID 34203994, 2021). "In murine T-cell lymphoma, aberrant expression of neighboring DLX5 and DLX6 was correlated with inversion of chromosome 6, juxtaposing the loci of these NKL homeobox genes with T-cell receptor gene Tcrb." (PMID 34829904, 2021). "Pathological analysis revealed that the T-cell lymphomas from Lck-Dlx5;Lck-MyrAkt2 mice frequently involved the lung as well as liver, kidney, spleen and bone marrow." (PMID 32985581, 2020). "A search for published studies in expression repositories such as GEO and ArrayExpress websites revealed five studies of human T-cell ALL or T-cell lymphoma containing DLX5 expression data." (PMID 28122332, 2017). "The resulting spontaneous T-cell lymphomas maintain addiction to Dlx5 through further intensified Notch and Akt signaling, thus connecting the Dlx5 homeoprotein to two pathways that are also known to be critically involved in the proliferation and survival, respectively, of human T-ALL." (PMID 28122332, 2017). "For example, DLX5 is abundantly expressed in a subset of adult human T-cell lymphomas, and DLX5 may contribute to tumorigenesis by directly regulating MYC expression." (PMID 28122332, 2017). "We demonstrate for the first time that Dlx5 induces T-cell lymphomas with high penetrance." (PMID 28122332, 2017). "DLX5 expression was also detected in primary human T-cell lymphoma samples while DLX6 tested negative." (PMID 34829904, 2021). "However, DLX5 mRNA, but not DLX6 mRNA, was abundantly expressed in three of seven human T-cell lymphomas we tested." (PMID 34203994, 2021).
breast carcinoma (4 papers, 2010 to 2021). "The central genes of the network were identified and RUNX1, PAX3, GATA4 and DLX5 genes were subjected for epigenetically dysregulation in association with diversity of breast cancer subtypes." (PMID 28747748, 2017). "The central genes of the network (RUNX1, PAX3, GATA4 and DLX5) were subjected for epigenetically dysregulation in association with different breast cancer subtypes." (PMID 28747748, 2017). "Although it is the first time to reveal DLX5 hypermethylation in myeloid neoplasms, previous study has also proved the phenomena of DLX5 methylation in breast cancer and neuroblastoma tumors by genome‐wide methylation analysis." (PMID 32508046, 2020). "In the cluster DLX5/DLX6, the phenomena of DLX5 hypermethylation was identified in breast cancer, neuroblastoma tumors, and colorectal cancer." (PMID 32508046, 2020). "The expression of DLX2 and DLX5 was evaluated in 408 primary human breast cancers examining the GSE1456 and GSE3494 microarray datasets." (PMID 21108812, 2010). "A preliminary analysis on human samples showed inhibition of DLX2 and induction of DLX5 expression in breast cancer, as compared with normal breast tissue." (PMID 21108812, 2010). "Herein we show that a DLX2-to-DLX5/6 switch in gene expression occurs during metastasis formation by MDA-MB-231 human breast carcinoma cells injected into nude mice." (PMID 21108812, 2010). "Moreover, expression of DLX2 and DLX5 have been reported to be mutually exclusive in breast cancer, with DLX2 expression being significantly correlated with a favorable prognosis, whereas DLX5 was associated with metastasis." (PMID 34203994, 2021). "Our data suggest that DLX2 and DLX5 are involved in human breast cancer progression, and that they might serve as good or poor prognostic markers, respectively." (PMID 21108812, 2010). "To analyze the role of DLX2, DLX5, and DLX6 in breast primary tumor and metastasis formation, we used an experimental model of breast cancer metastasis." (PMID 21108812, 2010). "Our studies indicate that DLX genes are involved in human breast cancer progression, and that DLX2 and DLX5 genes might serve as prognostic markers." (PMID 21108812, 2010). "Furthermore, analysis of microarray data on human breast tumors showed that breast cancer patients with DLX2 expression had on average better prognosis and less incidence of relapse, while DLX5 expression and DLX2 downregulation, was related to a subset of more aggressive tumors." (PMID 21108812, 2010).
breast tumors (3 papers, 2010 to 2025). "In the present study we specifically investigated the involvement of DLX2 and DLX5/6 in breast tumor progression." (PMID 21108812, 2010). "The epigenetic dysregulation of DLX5 gene could be suggested as an indicator for aggressiveness of breast tumors." (PMID 28747748, 2017). "In order to assess the role of DLX2 and DLX5 gene expression also in humans, we performed a preliminary analysis of the DLX status on 2 samples of normal breast tissue and on 2 samples of primary breast tumor." (PMID 21108812, 2010).
cleft palate (3 papers, 2014 to 2016). Cleft palate is a fissure type embryopathy that affects the soft and hard palate to varying degrees. "Sequencing of DLX5 and DLX6 in a cohort of humans with isolated cleft palate has shown causal effects of missense mutations in DLX5." (PMID 28053980, 2016). "A genome-wide association study of Nova Scotia Duck Tolling Retrievers with naturally occurring cleft palate led to the investigation of two homeobox genes, DLX5 and DLX6." (PMID 24699068, 2014).
craniosynostosis (3 papers, 2016 to 2025). Craniosynostosis is defined as the premature fusion of one or more cranial sutures leading to secondary distortion of skull shape resulting in skull deformities with a variable presentation. "In fact, GWASs on non-syndromic craniosynostosis have identified risk SNPs near BMP2, BMP7, BMPER, and DLX5, which overlap with loci identified here, and are directly linked to RUNX26,111–115." (PMID 40087503, 2025). "Computed tomography scans showed parietal foramina in the OsxCre;Stat3fl/fl mice and morphological deformities including a circular shape and craniosynostosis that were similar to the phenotype of the Msx1 and Dlx5 deletion mice." (PMID 34824272, 2021).
Rett syndrome (3 papers, 2005 to 2024). A severe neurodevelopmental disorder affecting the central nervous system.